FASN (fatty acid synthase)
Diseases named in the same sentence as FASN in open-access papers (continued):
Sharing a sentence is not in itself a finding about the gene and the disease.
prostate carcinoma (continued). "In another example, a sub-population of FASN in prostate cancer cells associates with lipid rafts and physically interacts with Cav-1, which must be palmitoylated for the interaction to occur." (PMID 26659560, 2015). "USP2a (also known as USP2) has been implicated in prostate cancer through its deubiquitination and stabilization of fatty acid synthase and more recently Hdm2 as well as its closely related functional homolog HdmX." (PMID 25605410, 2015). "In prostate cancer (PCa), elevated levels of FASN have been linked to poor prognosis, reduced disease-free survival, aggressiveness of disease, and increased risk of death." (PMID 25313139, 2014). "Previous pathological studies have shown that FASN overexpression is strongly associated with prostate cancer progression and metastasis." (PMID 23741342, 2013). "It has been recently observed that FASN is associated with β-catenin stabilization in prostate cancer." (PMID 22485149, 2012). "Androgens are known to stimulate lipogenesis in prostate cancer cells directly by increasing the transcription of specific genes encoding lipogenic enzymes, such as the fatty acid synthase (FAS) and HMG-CoA reductase." (PMID 23185449, 2012). "Fatty acid synthase mRNA and protein upregulation is one of the earliest and most common events in the development of prostate carcinoma, and a strong association between FASN and tumour initiation has been shown." (PMID 17146477, 2007). "The only prior study of epigenetic regulation of FASN has suggested that HOXB13 may function to repress FASN expression in prostate cancer cells, while the HOXB13 G84E mutation may lead to FASN derepression and increased expression." (PMID 38112617, 2024). "Finally, combined loss of PTEN with FASN overexpression was associated with lethality as assessed in 660 prostate cancer patients with 14.2 years of median follow‐up." (PMID 33166087, 2021). "Overexpression of FASN and altered metabolism in prostate cancer cells are associated with inactivation of PTEN; in contrast, PTEN expression is inversely correlated with FASN expression in prostate cancer, while inhibition of PTEN leads to the overexpression of FASN in vitro." (PMID 33166087, 2021). "Progression of prostate cancer is associated with an increase in de novo fatty acid synthesis which is independent from systemic lipid levels with an increase in key enzymes in the lipogenic pathway, including fatty acid synthase (FASN) in metastatic CRPC." (PMID 34319488, 2021). "E3 ligase SPOP mutation, which is common in prostate cancer, inhibits its ubiquitination of FASN." (PMID 33004065, 2020). "In SDC, as well as prostate cancer, the expression of FASN might be associated with the expression of AR through the endoplasmic reticulum stress response." (PMID 32103349, 2020). "Indeed, FASN was indirectly associated with prostate cancer migration via degradation of the androgen receptor." (PMID 32139877, 2020). "Additionally, ETS variant 1 (ETV1) and fatty acid synthase (FASN) mRNAs identified in LNCaP- and PC-3- derived MVs highly correlated with prostate cancer progression." (PMID 28143451, 2017). "In prostate cancer, FASN overexpression increases palmitate ester synthesis and stabilizes β-catenin accumulation through Wnt-1-mediated palmitoylation, driving oncogenesis." (PMID 40977744, 2025). "The increased rate of de novo fatty acid synthesis in prostate cancer cells is closely related to FASN." (PMID 39944823, 2025). "Highlights the importance of FASN in regulating prostate cancer cell motility, supporting it as a potential therapeutic target." (PMID 40977744, 2025). "The E3 ligase SPOP regulates lipid metabolism by reducing FASN expression and fatty acid synthesis, leading to suppression of prostate cancer growth." (PMID 39944823, 2025).
prostate carcinoma (continued). "Studies related to prostate cancer have shown that p300 promotes tumour growth and regulates the expression of the lipid metabolism regulator FASN by acetylating H3 in the FASN gene promoter." (PMID 39778006, 2025). "A previous study has suggested that the ubiquitin-specific protease USP2a interacts with and removes ubiquitin from FASN, subsequently preventing ubiquitin-mediated degradation in prostate cancer." (PMID 38195819, 2024). "For example, c-Myc maintains the glycolytic activity and increases the expression of key fatty acid synthesis genes, such as ATP citrate lyase, acetyl-CoA carboxylase alpha, and fatty acid synthase, thus promoting prostate cancer progression." (PMID 39253786, 2024). "In the current study, we investigate FASN gene CpG methylation pattern in human prostate cancer samples." (PMID 38112617, 2024). "Here, we leverage multiple independent primary and metastatic prostate cancer cohorts to demonstrate that FASN gene body methylation is highly inversely correlated with FASN gene and protein expression." (PMID 38112617, 2024). "The FASN gene is recurrently amplified in up to one quarter of primary and metastatic prostate cancers, and gene amplification correlates with FASN protein expression to some extent." (PMID 38112617, 2024). "Human malignancies, such as breast, colon, and prostate cancer, have elevated expression and activation of FASN, leading to an upsurge in the production of triacylglycerides (TG) deposited in lipid droplets (LDs)." (PMID 38933330, 2024). "Therapies that inhibit lipid metabolic pathways include those targeting acetyl‐CoA carboxylase in non‐small cell lung cancer and hepatocellular carcinoma as well as those targeting FASN in lung, ovarian, and prostate cancers." (PMID 38874588, 2024). "Prostate cancer cells overexpress fatty acid synthase protein (FASN) and monoacylglycerol lipase (MAGL), both metabolic enzymes that promote the formation and breakdown of lipids, which are now thought to be metabolic oncogenes." (PMID 39596205, 2024). "Among these, USP2 interacts with FASN and promotes its protein stability by reducing the ubiquitination level of FASN in prostate cancer." (PMID 39489738, 2024). "In radiotherapy-resistant prostate cancer, a combination of FASN inhibition and radiotherapy decreased NF-kB activity and induced apoptosis, whereas in breast tumours, apoptosis was concomitant with pro-death BH3 family proteins BIM, PUMA, and NOXA." (PMID 38610991, 2024). "FASN gene amplification occurs in prostate cancer cells, correlating with protein expression and germline SNPs also correlated with expression, suggesting potential genomic regulatory mechanisms." (PMID 38112617, 2024). "Palmitoylation of caveolin-1, through the indirect activity of FASN, promotes the activation of Src and Akt which increases the migration of prostate cancer cells." (PMID 36934087, 2023). "A more recent study has found that the knockdown of MBTPS2 expression in human prostate cancer cells impaired cholesterol synthesis and uptake and reduced the expression of key regulators of fatty acid synthesis, FASN and ACACA, through SREBP signaling." (PMID 37958642, 2023). "Lipogenic alterations that commonly occur in prostate cancer are overexpression of the enzyme FASN and deregulation of the AMPK." (PMID 37214073, 2023). "Androgen-stimulated USP2a upregulation in prostate cancer has been shown to stabilize FASN expression by blocking its polyubiquitination." (PMID 38060103, 2023). "On the other hand, orlistat binds irreversibly to the thioesterase domain of FASN and inhibits the xenograft growth of prostate cancer cells." (PMID 37046804, 2023). "In studies related to prostate cancer, p300 was found to have a tumour-promoting effect and to regulate the expression of FASN, a regulator of lipid metabolism, by acetylating H3 in the FASN gene promoter." (PMID 36979352, 2023).
prostate carcinoma (continued). "Genetic ablation and pharmacological inhibition of FASN in prostate cancer cells significantly inhibited cell motility and invasion." (PMID 36855119, 2023). "Some studies have shown that the overexpression of oncogene MYC can lead to the imbalance of lipid metabolism, induce the expression of fatty acid synthase, and then promote the progression of prostate cancer." (PMID 36824662, 2023). "The overexpression of FASN in prostate cancer cells (LNCaP) increases cell proliferation and soft agar growth." (PMID 36934087, 2023). "Silencing FASN in prostate cancer leads to a reduction of RhoU palmitoylation and decreases the protein stability of Cdc42, which is connected to the suppression of migration and invasion." (PMID 38060103, 2023). "For instance, chromatin immunoprecipitation (ChIP) data has shown that MYC binds to the promoter regions of key lipid metabolic enzymes, ACLY, ACC, and FASN in prostate cancer." (PMID 37046804, 2023). "In preclinical models of mesothelioma, as well as in renal, lung, and prostate cancer it has been shown how FASN inhibition was able to modulate the proliferation and to induce apoptosis in cancer cells." (PMID 36578540, 2022). "[11C]Acetate is proposed to be a probe for FASN on the basis that its uptake correlates with FASN expression in multiple prostate cancer cell lines." (PMID 35268652, 2022). "In fact, FASN has been studied as a candidate oncogene in cancer such as prostate cancer, liver cancer, and ovarian cancer." (PMID 35350838, 2022). "Post-translational regulation of FASN is observed in prostate cancer by the isopeptidase, ubiquitin-specific protease-2a (USP2a), which removes ubiquitin from FASN preventing its degradation." (PMID 36618350, 2022). "PPARG activates lipid signaling pathways, and high levels of PPARG/FASN confer a poor prognosis in prostate cancer." (PMID 35874705, 2022). "That is, studies have confirmed that inhibition of FASN reduced triacylglycerol and phospholipid levels and inhibited lymph node metastasis of prostate carcinoma." (PMID 36568252, 2022). "Several studies have reported that FASN expression positively correlates to cancer stages, including prostate cancer, renal cancer, and colorectal cancer." (PMID 35742944, 2022). "Early studies that monitored FASN expression in primary prostate cancers showed that FASN expression was detected in 57% of 99 primary prostate cancers, which corresponded to decreased disease-free survival in patients." (PMID 35634242, 2022). "In contrast, ASC-J9 inhibited the expression of FASN and the growth and invasion of various prostate cancer cell lines mediated by FASN." (PMID 34295247, 2021). "The well-known prostate cancer marker gene, FASN, had a good distinction between tumor and normal patient samples in TCGA mRNA-seq as well as microarray data and our present proteome datasets." (PMID 34944692, 2021). "For instance, several studies have revealed that orlistat, as an antitumor drug, inhibits tumor growth in a variety of cancers, including prostate cancer, by inhibiting fatty acid synthase." (PMID 34804366, 2021). "SREBP-1 induced prostate cancer cell proliferation, migration and invasion in vitro and promoted prostate tumor growth through the induction of FASN expression and lipid droplet formation and accumulation in prostate cells." (PMID 33737530, 2021). "We confirmed the differential expression levels and further provided functional information of FASN in prostate cancer progression via in-vitro, in-vivo and clinical studies." (PMID 34944692, 2021). "Phase I studies of TVB-2640, the first FASN inhibitor to enter clinical trials for prostate cancer, indicated a favorable tolerability profile as either monotherapy or in combination with taxane in four heavily pre-treated prostate cancer patients." (PMID 35127483, 2021).
prostate carcinoma (continued). "To verify that Fasn knockout indeed results in decreased invasive potential, we show that genetic ablation and pharmacologic inhibition of FASN in prostate cancer cells significantly inhibit cellular motility and invasion." (PMID 33166087, 2021). "We have further investigated and obtained expression and functional information of FASN in prostate cancer progression." (PMID 34944692, 2021). "The results of the pooling analysis further affirmed that FASN expression was higher in bladder cancer, colorectal cancer, lymphoma, ovarian cancer, and prostate cancer tissues (P < 0.001) than in corresponding normal controls." (PMID 34879004, 2021). "The level of FASN protein expression in prostate cancer patient tissues was increased according to the increase of the grade and higher TNM stages, as shown in the prostate adenocarcinoma primary solid tumor from Illumina mRNAseq level_3 (v2) data set." (PMID 34944692, 2021). "Considering that the new FASN inhibitor TVB‐2640 is the first‐in‐class in clinical trials, the data provide a rationale for utilizing FASN inhibitors in the treatment of prostate cancer, especially those with Pten loss." (PMID 33166087, 2021). "FASN is overexpressed in human prostate cancer, especially in the metastatic, castration‐resistant setting, and is associated with poor prognosis." (PMID 33166087, 2021). "Fatty acid synthase (FASN) is a main enzyme participating in the formation of the newborn fat and is overexpressed in tissues of various tumors, such as prostate cancer and bone tumor." (PMID 34456997, 2021). "We performed a cell proliferation assay under two conditions: First, we transfected human prostate cancer cell lines LNCaP cells with siRNAs targeting FASN or USP14, either individually or together." (PMID 34948233, 2021). "FASN is the key enzyme for the control of fatty acid synthesis that contributes significantly to prostate cancer progression, and FASN was observed to be relatively high in castrated mouse xenograft tissues compared to intact ones." (PMID 34944692, 2021). "Several studies have reported that pharmacological or genetic FASN inhibition results in cell cycle arrest, apoptosis, and reduction of prostate cancer progression in xenograft models." (PMID 33166087, 2021). "Previous studies in prostate cancer were mostly conducted with FASN inhibitors such as C75, orlistat, and triclosan, whose off‐target effects as well as instability and poor solubility/oral availability have limited their use in the clinical setting." (PMID 33166087, 2021). "In support of this, pharmacological inhibition of another key enzyme in the fatty acid synthesis pathway, FASN (Fatty Acid Synthase), enhanced the effects of bortezomib in prostate cancer cells." (PMID 32851475, 2021). "Here, we demonstrated that FASN inhibits tumor progression by reducing the migration and invasion of Pten heterozygous prostate cancer cells." (PMID 33166087, 2021). "We now find depletion of FASN expression increases prostate cancer cell adhesiveness, impairs HGF-mediated cell migration and reduces 3D invasion." (PMID 32139877, 2020). "Whilst FASN has previously been reported to be important in the migration of several different cancers this is the first study to focus directly on FASN driven migration and invasion in advanced prostate cancer cell models." (PMID 32139877, 2020). "Nuclear localization of FASN was first reported in 2014 where it was shown to correlate with disease aggressiveness in prostate cancer." (PMID 32872164, 2020). "To test the clinical significance of our findings we analysed FASN, RhoU and Cdc42 in prostate cancer and adjacent benign tissue in a cohort of 85 men who underwent a radical prostatectomy." (PMID 32139877, 2020). "In prostate cancer, the upregulation of isopeptidase ubiquitin-specific protease 2a (USP2a) after androgen stimulation, is shown to stabilize FASN expression by preventing ubiquitin-mediated degradation." (PMID 32872164, 2020).
prostate carcinoma (continued). "We discovered that depletion of FASN in prostate cancer leads to a decrease in the palmitoylation of the atypical Rho GTPase RhoU." (PMID 32139877, 2020). "The effect of 3 FASN inhibitors on viability of 2 prostate cancer cell lines, PC3 and LNCaP cells, was assessed using the MTT assay." (PMID 33083663, 2020). "Prostate cancers, like many other types of cancer, express elevated levels of fatty acid synthase (FASN) to make more fatty acids, which are required for energy, signaling, and proliferation." (PMID 33083663, 2020). "FASN depletion reduced the migratory capability of prostate cancer cells in both 2D migration and 3D invasion assays." (PMID 32139877, 2020). "Androgen-stimulated prostate cancer cells can proteolytically cleave SREBP1c and induce its nuclear translocation and FASN upregulation." (PMID 32872164, 2020). "Because serum is a source of fatty acids, we further assessed differences in the response of prostate cancer cells to FASN inhibitors by carrying out experiments in reduced serum (1%) medium, thus reducing the availability of fatty acid." (PMID 33083663, 2020). "This is supported by the observation that addition of exogenous palmitate rescued the adhesion phenotype in FASN knockdown prostate cancer cells." (PMID 32139877, 2020). "We found that high FASN expression was an independent predictor of shorter BCR-free survival with univariate and multivariate survival analysis (p < 0.05), rendering FASN an optimal prognostic biomarker in male Han Chinese with prostate cancer." (PMID 32655718, 2020). "In summary, we have demonstrated that inhibitors of fatty acid synthase have distinct effects on cytotoxicity of prostate cancer cell lines." (PMID 33083663, 2020). "In prostate cancer, FASN and caveolin-1 are coordinately expressed where the levels of both proteins are seen increasing from normal to malignant state, and that the increment magnitude is in line with tumor progression." (PMID 32872164, 2020). "Currently, there is mounting evidence that suggests that FASN is involved in prostate cancer progression, however little is known about the pathways or proteins that act downstream of FASN." (PMID 32139877, 2020). "In prostate cancer, selective FASN inhibition antagonizes tumor growth through metabolic reprogramming and results in a reduced protein expression and reduced transcriptional activity of AR." (PMID 32103349, 2020). "For the protein-ligand interaction studies, we have selected the specific target proteins which are involved in lipogenesis and apoptosis pathway including FASN and Bcl-2 because prostate cancer survival depends on the lipogenesis pathway." (PMID 32258129, 2020). "It is considered that FASN is a bona fide oncogene based on its high expression in prostate cancer and its effect in protecting cancer cells from apoptosis." (PMID 32655718, 2020). "We have previously showed that the fatty acid synthase inhibitor C75 sensitized prostate cancer cells to ionizing radiation." (PMID 30774777, 2019). "Inhibition of FAS or FASN expression has been previously shown to sensitize prostate cancer and non-small cell lung cancer cells to irradiation However, FAS inhibition did not result in an increase in DNA damage or radiosensitization in HNSCC cell lines." (PMID 31817870, 2019). "Upstream proteins of FASN such as Akt and NF-κB are found increased in the radioresistant prostate cancer cells." (PMID 31527721, 2019). "Re-introduction of PTEN in PTEN-null prostate cancer or inhibition of the PI3K pathway also decreased expression of fatty acid synthase, demonstrating the importance of its role in prostate cancer." (PMID 30774777, 2019). "Prostate cancer progression is characterized by dysregulation of lipid metabolism, mediated by overexpression of fatty acid synthase (FASN), an enzyme playing a key role in de novo fatty acid synthesis." (PMID 31366128, 2019).